PLA2G6 (phospholipase A2 group VI)
Diseases named in the same sentence as PLA2G6 in open-access papers (continued):
Sharing a sentence is not in itself a finding about the gene and the disease.
Dystonia (52 papers, 2010 to 2026). An abnormally increased muscular tone that causes fixed abnormal postures. "The clinical features of PD with PLA2G6 mutations generally are levodopa responsiveness, dystonia, gait impairment, speech difficulties, spasticity, myoclonus, and an association with neuropsychiatric and cognitive disorders." (PMID 40362688, 2025). "Patients with phospholipase A2 group VI (PLA2G6) mutations consistently exhibit dystonia–parkinsonian syndrome at early‐age onset and comorbidities with neuropsychiatric symptoms." (PMID 41395455, 2025). "Similarly, mutations in iPLA2β (PLA2G6), which encodes a calcium-independent phospholipase, have been implicated in autosomal recessive early-onset parkinsonism, often presenting with dystonia and oropharyngeal involvement." (PMID 40823463, 2025). "Interestingly, there are several genetic factors directly or indirectly related to glycerophospholipid metabolism, such as PLA2G620, that are associated with PD risk (PLA2G6 is the cause of early-onset PARK14-linked dystonia- parkinsonism)." (PMID 35411052, 2022). "PLA2G6-associated neurodegeneration encompasses three overlapping phenotypes: infantile neuroaxonal dystrophy (INAD) and atypical neuroaxonal dystrophy (atypical NAD) have a pediatric onset, while a third form of dystonia–parkinsonism has an adult onset." (PMID 40724495, 2025). "Notably, we demonstrated that dystonia genes sharing a common molecular pathway, such as PLA2G6 and PANK2, can manifest opposite neural behaviors in the globus pallidus." (PMID 39887724, 2025). "The majority (n=43) were carriers of heterozygous variants in genes linked to dominantly inherited dystonia genes (ATP1A3, GCH1, SGCE, KMT2B, THAP1, TOR1A, and VPS16), while only one carrier of a homozygous PLA2G6 variant and one of compound-heterozygous PTS variants were identified." (PMID 40672488, 2025). "A homozygous missense mutation of PLA2G6 was confirmed to contribute to autosomal recessive early-onset parkinsonism (AREP) in Han Chinese families without dystonia." (PMID 33154736, 2020). "The clinical phenotype of the cases with PANK2 and PLA2G6 is remarkably similar in the initial stages of the two diseases when it would be very difficult to differentiate the two as both have developmental delay, spasticity and dystonia." (PMID 22416811, 2013).
infantile neuroaxonal dystrophy (46 papers, 2007 to 2025). "PLA2G6 encodes calcium-dependent phospholipase A2β, and biallelic pathogenic variants in this gene were initially associated with infantile neuroaxonal dystrophy and atypical neuroaxonal dystrophy, both of which manifest during infancy or early childhood." (PMID 40263418, 2025). "Initial studies reported that mutations in the gene encoding Ca2+-independent phospholipase A2 group 6 (PLA2G6) is the cause of infantile neuroaxonal dystrophy (INAD) and neurodegeneration with brain iron accumulation (NBIA)." (PMID 29108286, 2017). "Recessive mutations in the phospholipase A2 group VI (PLA2G6) gene have been initially described as the cause of infantile neuroaxonal dystrophy and neurodegeneration associated with brain iron accumulation." (PMID 25980689, 2015). "It was reported that mutations in the PLA2G6 gene are associated with two childhood neurologic disorders: infantile neuroaxonal dystrophy (INAD) and NBIA type 2." (PMID 26506412, 2015). "Mutations in PLA2G6 gene have variable phenotypic outcome including infantile neuroaxonal dystrophy, atypical neuroaxonal dystrophy, idiopathic neurodegeneration with brain iron accumulation and Karak syndrome." (PMID 24130795, 2013). "PLA2G6, a phospholipase recently associated with infantile neuroaxonal dystrophy, was downregulated in both LCPUFA groups." (PMID 17426818, 2007). "Finally, our genetic investigation based on whole exome sequencing followed by Sanger validation shown a novel insertion mutation in the PLA2G6 gene in an Iranian family with infantile neuroaxonal dystrophy." (PMID 35092705, 2022). "Recessive mutations in PLA2G6 were found to induce alterations in phospholipid metabolism and abnormal iron accumulation, which ultimately led to infantile neuroaxonal dystrophy (INAD), atypical neuroaxonal dystrophy (ANAD) and neurodegeneration with brain iron accumulation (NBIA)." (PMID 34356877, 2021). "Mutations in PLA2G6 could cause neurodegeneration including infantile neuroaxonal dystrophy and adult-onset dystonia parkinsonism." (PMID 30718471, 2019). "PLA2G6‐associated disease may have previously represented infantile neuroaxonal dystrophy (INAD) before NBIA reclassification." (PMID 25870938, 2016). "The proband exhibited gait problems, developmental regression (DQ 46.6), and an abnormal occipital cistern via head MRI at the age of 4, consistent with PLA2G6-linked infantile neuroaxonal dystrophy 1 (OMIM#256600), suggesting the unidentified CNV could be genuine." (PMID 38982507, 2024). "Of particular interest is mutations in PLA2G6 have been linked to several neurological diseases including infantile neuroaxonal dystrophy (INAD), neurodegeneration with brain iron accumulation (NBIA), hereditary spastic paraplegia (HSP) and PD, but the underlying mechanism is still unknown." (PMID 35645773, 2022). "Infantile neuroaxonal dystrophy (INAD) is a rare hereditary neurological disorder caused by mutations in the PLA2G6 gene." (PMID 29739362, 2018). "Mutations in PLA2G6 were identified in patients with a spectrum of neurodegenerative conditions, such as infantile neuroaxonal dystrophy (INAD), atypical late-onset neuroaxonal dystrophy (ANAD) and dystonia parkinsonism complex (DPC)." (PMID 27196560, 2016). "We describe the clinical phenotypes, neuroimaging features and PLA2G6 mutations in 5 children, of whom 4 presented with infantile neuroaxonal dystrophy (INAD)." (PMID 24745848, 2014). "Mutations in the PLA2G6 gene (Entrez GeneID:8398) have been identified in autosomal recessive neurodegenerative diseases classified as infantile neuroaxonal dystrophy (INAD), neurodegeneration with brain iron accumulation (NBIA), and dystonia-parkinsonism." (PMID 20886109, 2010). "PLA2G6 (iPLA2-VIA/iPLA2β) has been reported as the causative gene for an autosomal recessive form of PD (PARK14), infantile neuroaxonal dystrophy (INAD), and neurodegeneration with brain iron accumulation (NBIA)." (PMID 32392751, 2020).
infantile neuroaxonal dystrophy (continued). "In PLA2G6-associated neurodegeneration (PLAN), formerly called Seitelberger disease, a variety of neurological deficits are present from infancy, suggesting the importance of PLA2G6 in the brain." (PMID 27030050, 2016). "PANK2, COASY, PLA2G6, and other genes related to iron homeostasis have been reported to cause diseases related to abnormal iron accumulation, such as neurodegeneration with brain iron accumulation (NBIA) and infantile neuroaxonal dystrophy (INAD)." (PMID 32457446, 2020). "Key distinctions in phenotypic presentation and age of onset between classical infantile neuroaxonal dystrophy (INAD) and atypical neuroaxonal dystrophy (NAD), both representing clinical variants within the spectrum of PLA2G6-related neurodegeneration." (PMID 40717733, 2025). "Biallelic variants of PLA2G6 cause three neurological disorders: early adulthood-onset dystonia-parkinsonism (PARK14, OMIM# 612953), early childhood to juvenile-onset atypical neuroaxonal dystrophy (OMIM# 610217), and infantile neuroaxonal dystrophy (INAD, OMIM# 256600)." (PMID 36875645, 2023). "Infantile neuroaxonal dystrophy (INAD, OMIM#256600) is a major subtype of PLA2G6-associated neurodegeneration (PLAN), characterized by severe progressive neurodegeneration caused by PLA2G6 mutations that are inherited in an autosomal recessive mode." (PMID 35873758, 2022). "The PLA2G6 gene is responsible for an autosomal recessive form of PD (PARK14), as well as infantile neuroaxonal dystrophy and neurodegeneration with iron accumulation in the brain, all of which show LB pathology." (PMID 39201619, 2024). "Infantile neuroaxonal dystrophy (INAD) and PLA2G6-related dystonia-parkinsonism are the main two subtypes." (PMID 37403138, 2023). "PLA2G6-associated disease is a continuum of three distinct, yet overlapping phenotypes: classic infantile neuroaxonal dystrophy (INAD) (MIM#256600), atypical neuroaxonal dystrophy (NAD) of childhood-onset (MIM#610217) and PLA2G6-related dystonia-parkinsonism with onset in adulthood (MIM#612953)." (PMID 24745848, 2014).
atypical neuroaxonal dystrophy (19 papers, 2013 to 2025). "Later PLA2G6 pathogenic variants were identified in atypical neuroaxonal dystrophy (ANAD) and parkinsonian syndrome including adult onset dystonia parkinsonism (DP) and autosomal recessive early-onset parkinsonism (AREP)." (PMID 35911906, 2022). "Karak syndrome was described in two adolescent siblings with mutations in PLA2G6 gene who suffered, since age 6 years, from slowly progressive ataxia associated with cognitive decline." (PMID 24130795, 2013).
Adult-onset dystonia-parkinsonism (16 papers, 2016 to 2024). Adult-onset dystonia-parkinsonism is a rare neurodegenerative disease usually presenting before the age of 30 and which is characterized by dystonia, L-dopa-responsive parkinsonism, pyramidal signs and rapid cognitive decline. "Mutations in PLA2G6 have been associated with several neurodegenerative disorders, including adult-onset dystonia-parkinsonism, PARK14." (PMID 31118888, 2019). "PLA2G6 mutations may also result in another phenotype—autosomal recessive, adult-onset dystonia-parkinsonism (also called PARK14)." (PMID 35328025, 2022). "PLA2G6 mutations have been previously identified in patients with INAD and adult-onset dystonia-Parkinsonism (PARK14; OMIM 612953)." (PMID 28107443, 2017). "In 2009, PLA2G6 was reported as the gene responsible for another autosomal recessive neurodegenerative disease, early- and adult-onset dystonia-parkinsonism (PARK14)." (PMID 27078024, 2016). "However, adult-onset dystonia-parkinsonism mutations do not impair PLA2G6 catalytic activity but may modify substrate preferences or its regulatory mechanisms." (PMID 29440694, 2018).
neuroaxonal dystrophy (16 papers, 2012 to 2025). A nonspecific term referring both to the pathologic finding of swelling of distal portions of axons in the brain and to disorders which feature this finding. "Pathogenic variants in the PLA2G6 gene, encoding phospholipase A2, are recognized to be the fundamental reason for infantile neuroaxonal dystrophy." (PMID 35092705, 2022). "We report a Japanese individual with neuroaxonal dystrophy that was associated with a novel compound heterozygous mutation in a splicing site of the PLA2G6 gene." (PMID 24252552, 2013). "In contrast to neuroaxonal dystrophies due to mutation of the phospholipase A2, group VI (PLA2G6) gene, in which Lewy body pathology is widespread, no α-synuclein accumulation was detected in any of our PKAN cases." (PMID 22416811, 2013). "Here, we report a Japanese individual with neuroaxonal dystrophy associated with compound heterozygous mutations in the PLA2G6 gene." (PMID 24252552, 2013). "The neuropathological examination of only 1 case with a confirmed PLA2G6 mutation has been reported in a patient with atypical neuroaxonal dystrophy and an age of onset of 3 years." (PMID 20619503, 2012). "Our results demonstrate the clinical heterogeneity of neuroaxonal dystrophy with PLA2G6 gene mutations and support a genetic clinical view that compound heterozygous mutations that potentially result in residual protein function are associated with a less severe phenotype." (PMID 24252552, 2013). "Moreover, the presence of LB and NFT pathology has been described in neuroaxonal dystrophy with PLA2G6 gene mutation." (PMID 24252552, 2013). "When onset of PLA2G6-associated neurodegeneration is later the phenotype may be atypical (atypical neuroaxonal dystrophy)." (PMID 23814539, 2013). "To expand the neuropathological spectrum of neuroaxonal dystrophy caused by PLA2G6 mutations and investigate the overlap with other parkinsonian disorders, we identified 7 genetically-proven cases with infantile through to adult onset disease and report the clinical and neuropathological features." (PMID 20619503, 2012). "Additionally, recent findings suggest that GLP-1 receptor agonists may ameliorate neurodegeneration in murine models of infantile neuroaxonal dystrophy linked to PLA2G6." (PMID 40362326, 2025). "Moreover, earlier case reports describing neuroaxonal dystrophy or brain iron accumulation with abundant LBs may have been describing patients with PLA2G6 gene mutations." (PMID 24252552, 2013). "Thus, further investigations on the process of LB formation caused by loss of PLA2G6 gene function may provide new insights into the pathological mechanism of neuroaxonal dystrophy and LB formation." (PMID 24252552, 2013). "Recently, it was reported that mutations in the PLA2G6 gene cause INAD, but neuropathological analysis of genetically confirmed individuals with neuroaxonal dystrophy has been limited." (PMID 24252552, 2013). "PLA2G6 and ECHS1 gene sequence analysis was performed to rule out infantile neuroaxonal dystrophy (INAD) and bilateral striatal necrosis, respectively." (PMID 34246313, 2021).
melanoma (15 papers, 2013 to 2026). A malignant, usually aggressive tumor composed of atypical, neoplastic melanocytes. "The polymorphism of PLA2G6 associates with many malignant tumors, which includes gastrointestinal cancer and melanomas." (PMID 39062787, 2024). "Through genome-wide association studies (GWAS), single nucleotide polymorphisms (SNPs) in the loci PLA2G6 were associated with nevus counts and melanoma risk, and PLA2G6 was considered as a low penetrance risk gene for melanoma." (PMID 35340268, 2022). "In our study, KEGG analysis shows that PLA2G6 knockdown was associated with ferroptosis process in melanoma." (PMID 35340268, 2022). "Several PLA2 isoforms, i.e., pla2g6, pla2g7 and pla2g10, appeared to be upregulated in zebrafish V12RAS-driven melanoma, and PLA2G6 gene was associated with melanoma risk in humans." (PMID 33121001, 2020). "The FTO and PLA2G6 genes, which show significant associations with melanoma in both species, have been more classically studied in the light of metabolism and adiposity traits." (PMID 29963229, 2018). "Our findings on the biological function of PLA2G6 and the underlying association between PLA2G6 and ferroptosis in melanoma may contribute to developing a potential therapeutic strategy for melanoma." (PMID 35340268, 2022). "Moreover, PLA2G6 has also been linked to melanoma in the literature." (PMID 35340268, 2022). "In addition, we established the association between PLA2G6 and ferroptosis in the melanoma cells through proteomics that may inspire PLA2G6-targeted therapeutic strategies." (PMID 35340268, 2022). "The knockdown of PLA2G6 (Phospholipase A2 Group VI) was found to suppress the progression of melanoma by affecting the phenotypes of melanoma cells, inhibiting cell proliferation, migration, and invasion, promoting tumor cell apoptosis." (PMID 37210507, 2023). "To explore the possible molecular mechanism of action of PLA2G6 in melanoma, we used TMT quantitative proteomics technology to compare the whole-cell proteomes in control and PLA2G6 knockdown M14 cells." (PMID 35340268, 2022). "Although literature exists linking PLA2G6 to melanoma, the expression level of PLA2G6 and its biological role in melanoma is still unclear." (PMID 35340268, 2022). "Next, the CCLE data indicates that the expression of PLA2G6 was increased in melanoma cell lines, which is consistent with the Oncomine analysis." (PMID 35340268, 2022). "In conclusion, silencing PLA2G6 markedly impaired the migration and invasion behavior of melanoma cells." (PMID 35340268, 2022). "To characterize the PLA2G6 activity in vitro, we further examined the mRNA and protein expression level of PLA2G6 in normal human epidermal MC and four typical melanoma cell lines M14, SK-MEL-28, A375, and A875." (PMID 35340268, 2022). "Scratch wound and transwell assays showed that knockdown of PLA2G6 reduced migration and invasion in melanoma cells." (PMID 35340268, 2022). "Together, these results suggested that PLA2G6 knockdown significantly inhibited cell proliferation, metastasis, and promoted apoptosis in melanoma." (PMID 35340268, 2022). "The effect of PLA2G6 on melanoma metastasis was investigated by scratch wound assay and transwell assay." (PMID 35340268, 2022). "In this study, we detected the functions of PLA2G6 in the progression of melanoma and demonstrated that PLA2G6 played an oncogenic role in melanoma by up-regulating cell proliferation, migration, invasion and down-regulating cell apoptosis." (PMID 35340268, 2022). "The results also included 10 SNPs previously identified for melanoma risk reported at MC1R (2 SNPs), MX2, TERT/CLPTM1L, PLA2G6, CASP8, ACTRT3, ASIP, CDC91L1, and ARNT/SETDB1/LASS2ANXA9/MCL1/CTSK." (PMID 27993549, 2017). "For population based melanoma, recent large scale genome wide association studies in melanoma and naevi have discovered new common low penetrance genes (MTAP, PLA2G6, TERT and IRF4 for example) associated with both naevi number and melanoma." (PMID 23796690, 2013).
melanoma (continued). "Interestingly, PLA2G6 also mitigates ferroptosis in melanoma cells by regulating the transport of iron ions." (PMID 40860809, 2025). "PLA2G6 affects melanoma cells proliferation through ferroptosis and apoptosis." (PMID 40860809, 2025). "In human melanoma tissues, PLA2G6 expression is upregulated compared to adjacent tissues." (PMID 40860809, 2025). "Consequently, further exploration into the role of PLA2G6 in melanoma deserves to be conducted to unveil its potential as a therapeutic target." (PMID 40860809, 2025). "Melanoma is a malignant type of tumor, and the overexpression of PLA2G6 has been reported." (PMID 39062787, 2024). "Indeed, all genes associated with nevus count or cutaneous nevi in cluster 6 (MTAP, TUBBP1, PLA2G6, ERVFRD.3, TMEM184B, BAIAP2L2) were only associated with melanoma." (PMID 38308491, 2024). "Hence, we used those two cell lines as models to assess the biological effects of PLA2G6 on melanoma." (PMID 35340268, 2022). "Through CCK8 assay, cell clonal formation, and xenograft model of nude mice, we found that the proliferation of melanoma cells was significantly attenuated after PLA2G6 knockdown, suggesting that PLA2G6 can promote the proliferation of melanoma cells in vitro and in vivo." (PMID 35340268, 2022). "The results showed that the mRNA level of PLA2G6 was notably up-regulated in melanoma tissues." (PMID 35340268, 2022). "In vivo, PLA2G6 was also elevated in nine melanoma tissues compared to adjacent tissues." (PMID 35340268, 2022). "Moreover, comparison of the porcine results to those reported by human melanoma GWAS indicated shared association signals notably at CDKAL1 and TERT loci but also nearby CCND1, FTO, PLA2G6 and TMEM38B-RAD23B loci." (PMID 29963229, 2018). "Out of 20 orthologues of human melanoma-associated loci, 12 contained SNPs with p-values < 10–2 in the MeLiM model, and 6 of them had SNPs reaching a p-value < 10–3: CDKAL1 on SSC7, FTO on SSC6, PLA2G6 on SSC5, TMEM38B-RAD23B on SSC1 and SLC45A2 and TERT on SSC16." (PMID 29963229, 2018). "Although previous research described the relationship between ferroptosis and melanoma, no finding has been reported whether PLA2G6 is involved in this process in melanoma." (PMID 35340268, 2022).